CD4 (CD4 molecule)
Diseases named in the same sentence as CD4 in open-access papers (continued):
Sharing a sentence is not in itself a finding about the gene and the disease.
tumor (continued). "It has been demonstrated that cytotoxicity against tumor is dependent on an appropriate CD4+ and CD8+ T cell interaction." (PMID 23210562, 2012). "Even mortality from causes thought unrelated to HIV and the rate of HIV related neoplasms increased with decreasing CD4 cell count." (PMID 22448150, 2012). "The rational base of vaccines is that tumor Ag must be captured by dendritic cells, which migrate to lymph nodes to activate CD4 and CD8 cells, triggering an adaptive immune response." (PMID 22924051, 2012). "Although CD8+ T cells are directly responsible for lysis of infected cells and tumor cells, recent studies have shown that peptide immunization in the presence of CD4+ T cells enhances CD8+ T cell responses." (PMID 22563434, 2012). "Ag-specific CD4+ T cells play an important role in induction and regulation of anti-viral and anti-tumor immunity." (PMID 22879946, 2012). "CD8+ T cell-mediated type 1 immune responses can enhance the accumulation of distinct endogenous CD8+ and CD4+ T cells and facilitate their antitumor function within the tumor microenvironment." (PMID 22420471, 2012). "These professional antigen-presenting cells endocytose TSA, process it, and display antigenic peptides on their MHC class II molecules for recognition by tumor-specific CD4+ T cells." (PMID 22649466, 2012). "Combined PSK and docetaxel treatment led to a lower decrease in number of white blood cells than docetaxel alone, an effect accompanied by increased numbers of tumor-infiltrating CD4+ and CD8+ T cells." (PMID 22159900, 2012). "CD4+ T cells have beenshown to be essential for expansion of memory cells for tumor infiltration by CD8+ T cells and optimal function ofCD8+ T cells at the effector phase." (PMID 22415314, 2012). "In a recent paper, Ding and Zhou described the role of CD4+ T-cells and their subsets in tumor immunity." (PMID 23118782, 2012). "Together, these observations suggest CD4+ T cells respond to tumor antigens presented via MHC II to induce an effective immune response and emphasize the importance of transcriptional regulation of MHC II genes in cancer cells." (PMID 22563434, 2012). "Tregs infiltrate human cancers, and their prevalence in tumour-infiltrating lymphocytes is much higher than their proportion in peripheral blood, constituting 20% or more of tumour-infiltrating CD4+ lymphocytes." (PMID 22778767, 2012). "We have archived a series of these tumor samples and analyzed the CD4 and CD8 expression profile of each tumor." (PMID 22393458, 2012). "In contrast, activation of CD4+ T can have an important complementary role in the anti-tumor response." (PMID 22359669, 2012). "Emerging evidence indicates that CD4+ T cells possess cytotoxic potential for tumor eradication and perforin/granzyme-mediated cytotoxicity functions as one of the important mechanisms for CD4+ T cell-triggered cell killing." (PMID 23145026, 2012). "Whiteside’s group reported that tumor-derived microvesicles induce the expansion of CD4+ CD25+ FoxP3+ cells while inducing apoptosis of tumor-reactive CD8+ T cells." (PMID 22738135, 2012). "The anti-tumor efficacy of the ESC/STO-GM vaccine also correlated with significantly higher intra-tumoral CD8+ T/CD4+CD25+Foxp3+ Tregs ratio." (PMID 22860107, 2012). "The emerging evidence that chemotherapy can profoundly drive the effector development of tumor-specific CD4+ T cells implicates a new direction for chemoimmunotherapy, which aims to capitalize on the antitumor potential of CD4+ effector T cells." (PMID 22400040, 2012). "Fewer CD3+, CD3+CD4+ T cells in peripheral blood from obese than lean mice led to tumor survival and increased growth in obese mice relative to lean mice." (PMID 23170114, 2012). "As the tumor progresses and becomes established in the host, the population of TILs is skewed to favor regulatory T cells over the helper CD4+ T cells." (PMID 22693525, 2012).
tumor (continued). "Through the description of successful preventive or therapeutic experimental approaches to vaccinate the host against the tumor we will show that optimal activation of MHC class II-restricted tumor specific CD4+ T helper cells can be achieved in various ways." (PMID 22849661, 2012). "It was widely accepted that not only CTLs but also tumor antigen-specific CD4+ T cells participated in the anti-tumor immune responses through a variety of mechanisms." (PMID 23028615, 2012). "The addition of CTLA-4 blockade further increased IFN-γ production from CD4+ effector T-cells in the vaccine draining node and the tumor." (PMID 21559358, 2011). "Mouse tumor-models support the significance of cognate interactions between CD4 T cells and macrophages." (PMID 22176642, 2011). "Numerous studies now demonstrate the generation of functional anti-tumor immunity as a result of transient CD4 T cell depletion." (PMID 22046294, 2011). "CD4+CD25+ regulatory T cells (Treg cells) are expanded in murine tumor models, and their deletion can lead to complete tumor regression." (PMID 21904560, 2011). "In OTII/Foxp3EGFP mice, at most 0.2% of CD4 T cells retrieved from B16-OVA tumor-bearing mice express Foxp3EGFP." (PMID 22112546, 2011). "This review focuses on one of these obstacles and a pivotal step for the priming of tumor-specific CD8+ and CD4+ T cells; the in vitro loading of DCs with tumor antigens." (PMID 24212804, 2011). "These antigen-loaded mature DC are given back to the patient for stimulating a tumor antigen specific immune response that ideally stimulates both antigen specific CD4+ and CD8+ T-cells." (PMID 24212951, 2011). "The increase and accumulation of CD4+ Tregs in circulating PBMCs and tumor tissues have been observed in many kinds of malignancy, including NPC." (PMID 22051182, 2011). "Foxp3+CD25+CD4+regulatory T (T reg) cells constitute about 5–10% of peripheral CD4+T cells and control immunological self-tolerance and tumor immunity." (PMID 21533081, 2011). "Indicative of a CD4+-mediated response, adoptive transfer of purified antibodies from the immunized mice results in an anti-tumor response in vivo and apoptosis of endothelial cells in vitro." (PMID 21385454, 2011). "We showed recently that tumor skewed IL10-producing M2 macrophages can fully revert to IL12-producing M1 macrophages following interaction with CD4+ Th1 cells or with CD40-L-expressing cells in the presence of IFNγ." (PMID 22176642, 2011). "In conclusion, transfer of the MHC class I restricted TCR, derived from CTL clone A9, together with CD8 into recipient CD4+ T cells resulted in functional activity against peptide loaded target cells as well as (model-) tumor cells." (PMID 21892941, 2011). "While percentage of these cells was nearing 50% of the total CD4+ cells in the tumor infiltrating lymphocytes of control mice, it was just half in the MIP treated group." (PMID 21984926, 2011). "Induction of antitumor immunity depended on the ability of the MHC-II-positive tumor cells to trigger CD4+ T cells, which in turn induce stimulation and maturation of CTL effectors." (PMID 22110523, 2011). "Another approach focuses attention on potentiating the cellular component of the anti-tumor immune response targeting the immunosuppressive CD4+CD25+ T-regulatory cells." (PMID 24212824, 2011). "The total number of CD3+ and CD4+ T cells present in the tumor microenvironment was greatly reduced in WSX1-positive tumors." (PMID 21559505, 2011). "With regards to tumor-expressed self antigens, CD4 T cell help has been shown to improve primary CD8 T cell responses, prevent CD8 T cell tolerance by improving dendritic cell function, and support secondary recall responses upon viral vaccine boosting." (PMID 22046294, 2011). "While CD4 T cells were more often found scattered around the tumor glands, CD8 T cells and Bu1a+ staining was localized throughout the tissue and in tumor glands." (PMID 21356044, 2011).
tumor (continued). "In murine models, depletion of CD4+FoxP3+ Tregs enhances tumor rejection and improves therapeutic responses to cancer vaccines by promoting the function of CD8+ cytotoxic T lymphocytes." (PMID 24213115, 2011). "It is generally accepted that the generation of an effective anti-tumor and anti-infective immune response requires antigen presenting cells to prime cytotoxic T cells and CD4+T cells." (PMID 21984926, 2011). "Reciprocally, NK cells can activate DCs, enhancing their ability to produce pro-inflammatory cytokines and stimulate T helper and cytotoxic T lymphocyte responses of tumor-specific CD4+ and CD8+ T cells." (PMID 22013914, 2011). "Distinct from other co-stimulatory antibodies, we found that α4-1BB induced striking upregulation of KLRG1 on CD8+, and to a lesser degree CD4+, effector T-cells in the tumor." (PMID 21559358, 2011). "The tumor profile for Bird 17 at post-mortem (33 DPI) indicated a shared spectral profile for Vβ1 in kidney, testes and spleen (and in CD4+ cells isolated from kidney and spleen) and a second site-restricted tumor in the kidney comprising CD4+ Vβ2+ cells." (PMID 21573129, 2011). "Enrichment of CD4+CD25+regulatory T cells in tumor mass was found in various tumor animal model and clinical tumor patients." (PMID 21655250, 2011). "Whole tumor cells are a suitable source of tumor antigens for loading DCs in order to prime both CD4+ T helper and CD8+ cytotoxic T cells." (PMID 22082029, 2011). "Depletion of either CD8+ or CD4+ cells abrogated the protective effect of the vaccine, indicating that both cell types were participating in the anti-tumor immunity." (PMID 21385454, 2011). "In order to assess potential effects of downregulated CD1d expression by tumor on innate and adaptive antitumor immunity, we assessed spleens from tumor-implanted mice for levels of iNKT, NK, CD4+ and CD8+ T cells by FACS." (PMID 21695190, 2011). "Peptides STEAP281-296 and EZH295-109 function as strong CD4 T-cell epitopes that can elicit effective anti-tumor T-cell responses against STEAP or EZH2 expressing LC." (PMID 22053850, 2011). "Although the nature of the tumor complicates identification of CD4+ T cell responses the CD8+ TCRαβ+ T cells clearly represent a responding T cell population capable of specific recognition, cytokine production and anti-MDV capability." (PMID 21573129, 2011). "Previous reports have shown that the introduction of a CD8 independent TCR into CD4+ T cells resulted in production of cytokines after co-culture with peptide pulsed cells and cytotoxicity against tumor cells." (PMID 21892941, 2011). "By examining the absolute number of infiltrating KLRG1+ T-cells, however, we found that combination therapy results in 1.7-fold more CD4+KLRG1+ effector T-cells per mm3 of tumor relative to α4-1BB alone." (PMID 21559358, 2011). "α-TEA treatment resulted in higher frequencies of activated T cells in the tumor microenvironment and twofold and sixfold higher ratios of CD4+ and CD8+ T cells to regulatory T cells, respectively." (PMID 21232138, 2011). "Immunization of C57BL/6 mice bearing B16F10-HMW-MAA melanomas induced HMW-MAA-specific CD8+ and CD4+ T cells that were equally required for tumor inhibition, as in vivo depletion of each of these cells resulted in uncontrolled tumor growth." (PMID 21573118, 2011). "There was a correlation between clinical regression and increased MART-1-specific CD8+ T cells and a decrease in CD4+FoxP3+ Tregs at the tumor site." (PMID 24213115, 2011). "The fused microbial protein engages local CD4+ T cells to provide help for anti-tumor immunity, and to induce more potent CD8+ T cell responses able to suppress tumor growth." (PMID 24212974, 2011). "IL-21 mRNA was expressed concomitantly with IL-17 mRNA in tumor-bearing eyes and intracellular expression of IL-17A and IL-21 in infiltrating CD4+ T lymphocytes." (PMID 21949734, 2011).
tumor (continued). "∼40% of the CD4+ cells present in the tumor were Foxp3+ Tregs, demonstrating a selective recruitment of inhibitory cells to the tumor as a portion of total leukocytes compared to the TDLN." (PMID 21731676, 2011). "4-1BB expression is more pronounced on CD8 versus CD4 T-cells and for this reason most tumor immunity studies have focused on the impact of α4-1BB on this subset." (PMID 21559358, 2011). "TGF-β, produced in abundance by many types of tumor cells, promotes differentiation of naïve CD4+ T cells into Tregs." (PMID 24212948, 2011). "In contrast, we observed only low levels of IFN-γ production from CD4+ T-cells in the tumor draining lymph node." (PMID 21559358, 2011). "CD4 effector to Treg ratios in the tumor were also elevated in combination therapy, largely due to the effects of CTLA-4 blockade in promoting increased CD4 infiltration." (PMID 21559358, 2011). "Within CD4+ T cells derived from tumor sites, fourteen high frequency CDR3 (>50%) were identified with ten represented at greater than 70% of the sequences obtained." (PMID 21573129, 2011). "As summarized in the introduction section, slanDCs represent a major interesting subset of myeloid derived human blood DCs that is capable of inducing neoantigen-specific CD4+ T cells as well as tumor-reactive CD8+ CTLs." (PMID 21283706, 2011). "The authors showed that multiple vaccinations increased the absolute number of CD4+Foxp3+ Tregs in the peripheral blood and in the spleens, which decreased the therapeutic efficacy of splenocytes when adoptively transferred into tumor-bearing mice." (PMID 21859450, 2011). "Similar to the proportion of CD8+ T cells, that of CD4+ T cells was suppressed in late-stage tumor-bearing mice." (PMID 21352555, 2011). "In this study, we show that the presence of tumor-infiltrating CD4+CD25+ T cells are typical Tregs based on their CD4+CD25+FoxP3highCD45RO+CTLA-4+ phenotype and suppressive functions." (PMID 21935436, 2011). "Functional data revealed that slanDCs efficiently induce neoantigen-specific CD4+ T cells and activate tumor-reactive CD8+ cytotoxic T cells (CTLs)." (PMID 21283706, 2011). "In line with the other examined compartments CD4+CD25highFOXP3+CTLA-4+ Tregs were also increased in the tumor draining mesenteric lymph nodes (TDLNs)." (PMID 24212779, 2011). "In these studies, CD4 helper T cells were present early during priming, and again after surgical tumor excision, although the importance of CD4 T cell help for the development and maintenance of functional memory to tumor/self antigens has remained unclear." (PMID 22046294, 2011). "Increasing evidence shows that both tumor antigen-specific CD4+ and CD8+ T cells play a critical role in eradicating cancer." (PMID 21858191, 2011). "ST2 deletion enhances lymphopoiesis in local lymph node and spleen after tumor inoculation and increases the total number of CD4+ and CD8+ T cells." (PMID 21484786, 2011). "Accumulating data have indicated that Tregs were enriched in tumor mass and potently inhibited the anti-tumor immunity mediated by CD4+Th1 and CD8+CTL." (PMID 21655250, 2011). "In both cases the presence of multiple epitopes should be able to elicit polyspecific CD8+ and CD4+ memory responses against tumor cells." (PMID 24212974, 2011). "The drop in Tregs was accompanied by an increase in T cell responses against tumor cell lysates, a patients' response-rate of almost 70%, and restoration of the CD4+/CD8+ T cell ratio." (PMID 24212779, 2011). "In solid tumors, it has been suggested that CD4+CD25+ Treg are crucial cellular mediators in immune evasion by suppressing anti-tumor immunity and thereby contribute to the growth of human tumors." (PMID 22174855, 2011). "Deletion of CD4(+) T-lymphocytes abrogated the anti-tumor activity and endoglin-specific autoantibodies." (PMID 21385454, 2011).
tumor (continued). "In a similarly designed experiment but in knockout B-cell mice, the anti-tumor efficacy of the angiomotin vaccine was lost, indicating that CD4+ cells and a humoral immune response were essential." (PMID 21385454, 2011). "In contrast, type 2, IL-4 polarized CD4+ T cells (Th2) secrete cytokines which induce neutralizing antibody production by B cells, thus directing immunity towards a tumor-promoting type 2 response." (PMID 22190971, 2011). "Both antigen specific CD4+ and CD8 T+ cells are required to induce an optimal immune response that instructs macrophages, B cells for antibody responses by CD4+ T-cells and killing of the tumor cells by CD8+ cytotoxic T-cells." (PMID 24212951, 2011). "We confirmed that a significantly higher frequency of CD4+FoxP3+ Treg-cells were present in the tumor, as compared to normal colon (mean 9.095%±1.038% vs mean 0.478%±0.095%, p<0.0001)." (PMID 21559338, 2011). "This >10-fold drop in IFN-γ production in the tumor-draining relative to the vaccine-draining lymph node suggested that the most active, tumor-specific CD4+ T-cells had already trafficked into the tumor." (PMID 21559358, 2011). "The second strategy includes active immunisation, where antigen presenting cells (APCs) are loaded with TAA to induce full-blown anti-tumor responses that consist of effective CD4+ and CD8+ T-cell responses and prolonged memory." (PMID 24212951, 2011). "The spectratype profiles for whole tumor or sorted CD4+ cells from tumor sites in Birds 11 to 14 were similar to those seen with Bird 1 to 10, with dominant spectral peaks in tumor sites." (PMID 21573129, 2011). "It was shown that within the tumor microenvironment the tumor itself induces naïve CD4 cells to convert into antigen-specific Tregs." (PMID 22046558, 2011). "The results revealed that the combination therapy (AdhTERTHRP + AdCMVmIL-12) led to extensive tumor infiltration by CD4+ T cells (P < 0.0001, 9.4-fold) and CD8+ T cells (P < 0.0001, 8.6-fold) compared with AdCMV(-) group." (PMID 21481255, 2011). "Phagocytosed tumor antigens are either presented on MHC class II molecules which activate helper CD4+ T cells, or the antigen is cross-presented onto MHC class I molecules to activate antitumor cytotoxic CD8+ T cells." (PMID 22190938, 2011). "More importantly, the density of CD4(+) as well as CD8(+) T cells was highly correlated with tumor response to CRT." (PMID 21575175, 2011). "In both protective and therapeutic immunity models, the vaccine demonstrated anti-tumor activity through induction of CD4+-dependent antibodies." (PMID 21385454, 2011). "At the peak (day 8–10), there were relatively equal percentages of CD8+ and CD4+ T cells in the tumor (∼5%)." (PMID 21731676, 2011). "Due to their unique ability to prime and stimulate both CD8+ and CD4+ T cells, DCs loaded with whole tumor lysate have been investigated in several clinical trials for their ability to induce therapeutic anti-tumor T cell responses." (PMID 22194898, 2011). "Within this framework, we addressed the issue of T cell clonality during infection and tumor formation, dissecting the tumor, spleen and blood to identify repertoire changes in the transformed CD4+ cells and the responding CD8+ cells." (PMID 21573129, 2011). "Other reports have suggested that the number of circulating CD4 T lymphocytes is important for the suppression of tumor recurrence." (PMID 21306650, 2011). "A previous study has indicated that CD4+CD69+CD25− cells represented a new subset of regulatory T cells in the tumor model." (PMID 21887301, 2011). "The role for exosomes in biological processes has garnered considerable attention recently, mostly in the context of tumor antigen presentation and activation of CD4+ and CD8+ T cells." (PMID 21533172, 2011). "As slanDCs can induce neoantigen-specific CD4+ T cells and tumor-reactive CD8+ cytotoxic T cells, they appear as promising targets for an in vivo delivery of antigens for vaccination." (PMID 21283706, 2011).